CEP55 (centrosomal protein 55)
Diseases named in the same sentence as CEP55 in open-access papers (continued):
Sharing a sentence is not in itself a finding about the gene and the disease.
endometrial cancer (7 papers, 2023 to 2025). Primary or metastatic malignant neoplasm involving the endometrium (mucous membrane that lines the endometrial cavity). "And the axis circ-8073/miR-449a/CEP55 promotes endometrial cancer proliferation via the PI3K/AKT/mTOR pathway." (PMID 41283360, 2025). "Furthermore, upregulated expression of CEP55 greatly facilitates the progression of endometrial cancer, and conversely, decreased expression of CEP55 inhibits the proliferation and accelerates cell death." (PMID 40723362, 2025). "Moreover, CEP55 promoted tumorigenesis and indicated the poor prognosis in endometrial cancer." (PMID 40612112, 2025). "Moreover, abnormal expression of CEP55 significantly promoted endometrial cancer (EC) progression, whereas down-regulation of CEP55 expression could inhibit proliferation, invasion, migration, delay the cell cycle, and accelerate apoptosis." (PMID 37887301, 2023).
prostate carcinoma (7 papers, 2021 to 2026). A carcinoma that arises from epithelial cells of the prostate gland. "Concordantly, miR‐144‐3p has been elucidated to inhibit cancer cell proliferation and promote apoptosis by targeting CEP55 in the context of prostate cancer." (PMID 33417281, 2021). "The targeting relationship between CEP55 and miR‐144‐3p has been validated in prostate cancer cells." (PMID 33417281, 2021). "Interestingly, CEP55 expression was also elevated in twelve different cancer types, including colorectal, lung, breast, liver hepatocellular, kidney renal clear cell, kidney renal papillary cell, bladder urothelial, uterine corpus endometrial, stomach, thyroid, and prostate cancers." (PMID 38250876, 2024). "However, only NEIL3, CEP55, and DEPDC1B had a significant relationship with the prognosis of prostate cancer." (PMID 34591415, 2021).
renal cell carcinoma (7 papers, 2020 to 2025). "This study aims to clarify the mechanistic action of long non-coding RNA (lncRNA) SNHG12 in the development of renal cell carcinoma (RCC), which may be associated with promoter methylation modification by KMT2B and the regulation of the E2F1/CEP55 axis." (PMID 35597996, 2022). "Recently, researchers demonstrated that CEP55 promoted the epithelial-mesenchymal transition (EMT) and activated the PI3K/AKT/mTOR pathway in renal cell cancer." (PMID 37484531, 2023).
viral infection (7 papers, 2015 to 2025). "Similarly, in the GEO cohort, CEP55 expression was associated with tumor stage, survival status, tumor size, viral infection, and serum AFP level (p < 0.05)." (PMID 37484531, 2023). "Several differentially expressed genes between the two trajectories (CTSG, PRC1, DEFA4, KIF15, TCEAL9, HMMR, CEP55, and AZU1) were overexpressed in patients with severe viral infection, but not in those with non-severe viral infection compared to HCs." (PMID 33765435, 2021).
bladder cancer (6 papers, 2019 to 2025). "CEP55 was also reported to be upregulated in gastric, liver, lung, nasopharyngeal, and bladder cancers." (PMID 31612115, 2019).
cervical cancer (5 papers, 2020 to 2024). A primary or metastatic malignant neoplasm involving the cervix. "An analysis of the circular RNA‐miRNA‐mRNA network has revealed CEP55 as a potential mRNA implicated in the pathology of cervical cancer." (PMID 33417281, 2021). "Furthermore, overexpression of CEP55 in cervical cancer is associated with increased risk of lymph node metastasis and tumor progression." (PMID 38596293, 2024). "Largely in agreement with our findings, the expression of CEP55 has been reported to be 9‐fold higher when compared with adjacent normal tissues, which is associated with advanced tumour stage and a higher risk of lymph node metastasis in patients with cervical cancer." (PMID 33417281, 2021). "Two important oncogenic markers for cervical cancer were identified in another two studies, namely the centrosomal protein, 55 Kd (CEP55) and maternal embryonic leucine zipper kinase (MELK)." (PMID 38049868, 2023). "miR‐144‐3p was down‐regulated, whereas CEP55 was up‐regulated in cervical cancer cell lines and tissues." (PMID 33417281, 2021). "The expression of CEP55 was subsequently quantified in cervical cancer samples and normal samples that were available from the TCGA database." (PMID 33417281, 2021). "In this study, we explored the underlying mechanism of hBMSCs‐derived EVs and their involvement of interplay between miR‐144‐3p and CEP55 in the tumorigenesis of cervical cancer." (PMID 33417281, 2021). "CEP55 was targeted by miR‐144‐3p, which suppressed cervical cancer cell proliferation, invasion and migration and promoted apoptosis via CEP55." (PMID 33417281, 2021). "We found that CEP55 was up‐regulated in cervical cancer cells and tissues, thus contributing to the development and progression of cervical cancer." (PMID 33417281, 2021). "A functional report has demonstrated that CEP55 has the ability to reflect and indicate unfavourable clinical prognosis of patients suffering from cervical cancer, whereas the specific mechanism governing the action of CEP55 still requires further study." (PMID 33417281, 2021). "The results revealed that the expression of CEP55 was much higher in cervical cancer tissues than that in adjacent normal tissues, which was just in line with bioinformatics analysis in microarray data sets related to cervical cancer." (PMID 33417281, 2021). "CEP55 expression was elevated in cervical cancer cell lines HeLa, CaSki, SiHa and ME180, compared to that of the normal cervical epithelial cell line End1/E6E7, among which the SiHa cell line exhibited the highest expression of CEP55." (PMID 33417281, 2021). "The expression profiles of centrosomal protein, 55 Kd (CEP55) and miR‐144‐3p in cervical cancer cell lines and tissues, were quantified by RT‐qPCR and Western blot analysis." (PMID 33417281, 2021). "We then elucidated whether EVs could function as vehicles shuttling miR‐144‐3p into cervical cancer cells to regulate the expression of CEP55, so as to mediate the development of cervical cancer." (PMID 33417281, 2021). "Furthermore, an inverse relation between CEP55 and miR‐144‐3p was identified in our study and miR‐144‐3p was found to be expressed at a low level in cervical cancer cells and tissues." (PMID 33417281, 2021). "The results indicated that CEP55 was significantly highly expressed in cervical cancer samples." (PMID 33417281, 2021). "Increased CEP55 expression can be found in several cancers including endometrial cancer, bladder cancer, colorectal cancer, liver cancer, non-small cell lung cancer, renal cell carcinoma, cervical cancer, and esophageal squamous cell carcinoma and is generally associated with poor prognosis." (PMID 38596293, 2024). "Furthermore, the BMSC-derived exosomes could efficiently carry miR-144-3p or miR-375 into cervical cancer SiHa or C33A cells, playing significant inhibitory functions in the cell proliferation, invasion and migration via targeting CEP55 or MELK, respectively." (PMID 38049868, 2023).
cervical cancer (continued). "Taken together, overexpressed CEP55 potentiated the cellular capabilities of proliferation, migration, invasion and colony formation while inhibiting the capability of cell apoptosis, all of which could be reversed with the down‐regulated expression of CEP55 expression in cervical cancer." (PMID 33417281, 2021). "Following culture, the expression profiles of CEP55 in normal cervical epithelial cell line End1/E6E7 and cervical cancer cell lines, HeLa, CaSki, SiHa and ME180, were determined by RT‐qPCR and Western blot analysis." (PMID 33417281, 2021). "Therefore, CEP55 might play an important role in the development of cervical cancer." (PMID 33417281, 2021).
lymph node metastasis (5 papers, 2016 to 2021). "The clinical outcome of patients with high expression of CEP55 is associated with a poor prognosis and lymph node metastases." (PMID 34104194, 2021). "In our study, we found that aberrant CEP55 protein expression was significantly associated with lymph node metastasis and intraperitoneal metastasis." (PMID 26615423, 2016). "In further searching for more information about CEP55 in the UALCAN database, we found that the expression of CEP55 was also correlated with patient age, lymph node metastasis, and tumor stage." (PMID 33190424, 2021). "Our clinical data also showed that patients whose tumors had high CEP55 expression experienced more lymph node metastasis." (PMID 34104194, 2021). "High CEP55 expression was significantly related to clinical stage (p = 6.627e − 4), histological grade (p = 3.485e − 8), T classification (p = 7.367e − 5), lymph node metastasis (p = 0.017), histological type (p = 2.241e − 11), age (p = 0.001), survival status (p = 3.437e − 4), and sex (p = 0.015)." (PMID 32337246, 2020). "In our univariate analysis, stepwise inclusion of variables in the model indicated that significant prognostic factors included CEP55 protein level, lymph node metastasis, intraperitoneal metastasis, FIGO stage, differentiation grade, recurrence, age, CA153 serum level, and neoadjuvant chemotherapy." (PMID 26615423, 2016).
MARCH syndrome (5 papers, 2018 to 2025). "Functionally, loss of function of CEP55 leads to late gestational death, Meckel-like syndromes, and MARCH syndromes." (PMID 37887301, 2023). "The findings of KEGG and GO enrichment analyses show that CEP55 is involved in cell division, DNA repair, and apoptosis, and loss of CEP55 function can lead to fetal death at the end stages of pregnancy and the development of Meckel-like syndromes and MARCH syndromes." (PMID 40723362, 2025). "Nevertheless, these theoretical analogies linking CEP55 with RNF157 require further experimentation, especially since the hydranencephaly of the MARCH syndrome is associated with a defect in the recruitment of CEP55 to the midbody." (PMID 36497121, 2022).
microcephaly (5 papers, 2020 to 2024). A congenital or acquired developmental disorder in which the circumference of the head is smaller than normal for the person's age and sex. "The neural phenotypes in this model, including severe microcephaly with diminished cortical cellularity overlap with the human Cep55-associated disorders." (PMID 34710087, 2021). "This is made evident by human and mouse mutations of abscission genes that cause forms of microcephaly: Cep55, Kif20A, Kif20B, Kif14, CitK, and Sept7." (PMID 36303610, 2021). "Of note, proliferating cells and inhibitory neurons showed a mild, yet significant down-regulation of cell cycle and chromosome segregation genes, e.g., abnormal spindle-like, microcephaly-associated (Aspm), and Centrosomal Protein 55 (Cep55) which have been linked to craniofacial development." (PMID 38335290, 2024). "We suggest that defective PI3K/Akt pathway activation and consequently, increased apoptosis during embryogenesis could be the predominant cause of microcephaly seen in CEP55 loss-associated genetic syndromes." (PMID 34710087, 2021). "CEP55 loss in organoids led to size (area) decrease compared to control, consistent with microcephaly seen in CEP55-null human patients and mouse model." (PMID 34710087, 2021). "Cep55-knockout offspring show microcephaly and primary neural progenitors require Cep55 and ESCRT for survival and abscission." (PMID 32269212, 2020). "Although the body morphogenesis of Cep55−/− newborn mice appeared normal, the skull appeared flat, suggesting possible microcephaly." (PMID 32269212, 2020). "KIF14 (OMIM ID: 611279) and CEP55 (OMIM ID: 610000), like CIT, are recessively inherited etiologies of microcephaly, whereas variants in PPP1R12A (OMIM ID: 602021) are responsible for a de novo dominant form of a holoprosencephaly spectrum that includes individuals with microcephaly." (PMID 39316437, 2024). "Thus far, three of them, CEP55, KIF14, and CITK, have been associated with specific human microcephaly syndromes." (PMID 36303610, 2021). "However, Cep55-knockout newborns show severe microcephaly, reduced brain cortical thickness, binucleated neurons, and kidney abnormalities, similar to the features described in human infants affected by MARCH and Meckel-like syndromes." (PMID 32269212, 2020).
glioblastoma (4 papers, 2019 to 2023). The most malignant astrocytic tumor (WHO grade IV). "Elevated CEP55 mRNA expression was observed in 20 cancers, including glioblastoma multiforme (p < 0.05)." (PMID 37173675, 2023).
head and neck cancer (4 papers, 2012 to 2025). A primary or metastatic malignant neoplasm affecting the head and neck. "CEP55 (12-fold) encodes a centrosome-related gene where high expression was negative prognostic for head and neck cancer and its down-regulation inhibited migration and metastasis of cells." (PMID 22905093, 2012).
oral cancer (4 papers, 2009 to 2025). "Our finding that FOXM1 is upregulated early during oral cancer progression renders FOXM1 an attractive diagnostic biomarker for early cancer detection and its candidate mechanistic targets, CEP55 and HELLS, as indicators of malignant conversion and progression." (PMID 19287496, 2009). "However, at present, there is a lack of studies on CEP55 in oral cancer, and the value of CEP55 as a diagnostic and prognostic indicator of oral cancer is not clear." (PMID 40386043, 2025). "In conclusion, the potential of FOXM1B, CEP55 and HELLS as early oral cancer biomarkers deserves further investigation." (PMID 19287496, 2009). "Gene expression heatmap showed that CEP55 and MELK were highly expressed in oral cancer samples." (PMID 37589542, 2023).
renal dysplasia (4 papers, 2020 to 2023). Renal dysplasia is a form of renal malformation in which the kidney(s) are present but their development is abnormal and incomplete. "Disruption of CEP55 has recently been established in association with perinatal deaths characterized by hydranencephaly, renal dysplasia, oligohydramnios, and characteristic dysmorphisms." (PMID 37928238, 2023). "Mutation of the CEP55 gene is associated with multinucleated neurons, anhydramnios, renal dysplasia, cerebellar hypoplasia, and hydranencephaly (MARCH), a lethal autosomal-recessive fetal ciliopathy." (PMID 34944109, 2021). "Germline mutations of CEP55 in humans have been described in two lethal CEP55-associated syndromes, Meckel-Gruber syndrome (MKS)-like Syndrome and MARCH (Multinucleated neurons, Anhydramnios, Renal dysplasia, cerebral hypoplasia, and Hydranencephaly)." (PMID 34710087, 2021).
triple-negative breast carcinoma (4 papers, 2021 to 2024). An invasive breast carcinoma which is negative for expression of estrogen receptor (ER), progesterone receptor (PR), and human epidermal growth factor receptor 2 (HER2). "For validation, we also stably knocked-down CEP55 in the two triple-negative breast cancer cell lines MDA-MB-231 and MDA-MB-468." (PMID 39195269, 2024). "Our results showed that CEP55 was upregulated in luminal, HER2-positive, and triple-negative breast cancers compared to normal samples." (PMID 34055036, 2021).
breast tumors (3 papers, 2018 to 2021). "Gene expression studies implicated CEP55 in progression from in situ to invasive breast cancer, and overexpression in primary breast tumors is a marker of chromosomal instability and poor prognosis." (PMID 30108112, 2018). "Using TCGA data, we found that 20q is significantly more frequently gained than lost in breast tumor samples (15.6 versus 1.1%, P = 1.16 × 10−34) and tumors with 20q gain are significantly associated with higher CEP55 expression (P < 0.0001)." (PMID 30108112, 2018). "In summary, these data show that blocking MEK1/2/PLK1 substantially impacts tumor growth in multiple models of basal‐like, triple‐negative breast cancer and represents a novel candidate strategy for treating breast tumors that exhibit high CEP55 expression." (PMID 30108112, 2018). "In addition, 6/7 PC-CIN genes (CEP55, UBE2C, MELK, TPX2, PTTG1, and CDCA3) were also found to be among the top DEGs identified through comparison of high aneuploidy versus low aneuploidy breast tumors in TCGA." (PMID 32380981, 2020).
esophageal cancer (3 papers, 2021 to 2025). A primary or metastatic malignant neoplasm involving the esophagus. "CEP55 attenuated the suppressive effect of microRNA-148a-3p on proliferation and migration of esophageal carcinoma cells, demonstrating that microRNA-148a-3p regulated function of esophageal carcinoma cells via decreasing CEP55 level." (PMID 34952571, 2021). "qRT-PCR and western blot showed that CEP55 level in esophageal carcinoma cells and tissue was dramatically higher than that of normal cells and tissue, while microRNA-148a-3p was the opposite." (PMID 34952571, 2021). "We observed overexpression of CEP55 in esophageal cancer tissues after neoadjuvant immunotherapy." (PMID 38172247, 2024). "Thus, microRNA-148a-3p could act as a repressor in esophageal carcinoma via binding to CEP55." (PMID 34952571, 2021).
head and neck squamous cell carcinoma (3 papers, 2017 to 2024). A squamous cell carcinoma that arises from any of the following anatomic sites: lip and oral cavity, nasal cavity, paranasal sinuses, pharynx, larynx, and salivary glands. "CEP55 is a potential exosomal marker in head and neck squamous cell carcinoma." (PMID 38250876, 2024). "XRCC1 and CEP55 are supposed to be direct transcriptional targets of FOXM1 in serous EOC and head-and-neck squamous cell carcinoma, respectively." (PMID 28482906, 2017).
nasopharyngeal carcinoma (3 papers, 2012 to 2018). A carcinoma arising from the nasopharyngeal epithelium. "For example, increased CEP55 expression was reported to promote EMT in nasopharyngeal carcinoma via the osteopontin/CD44 pathway." (PMID 26615423, 2016). "Furthermore, some studies have identified the overexpression of CEP55 in colorectal carcinoma, prostate cancer, nasopharyngeal carcinoma, and gastric cancer." (PMID 26615423, 2016).